IL10 (interleukin 10)
Diseases named in the same sentence as IL10 in open-access papers (continued):
Sharing a sentence is not in itself a finding about the gene and the disease.
infection (continued). "Notably, the G strain‐infected group showed a significant and progressive increase in the production of the regulatory cytokine IL‐10 at 96 h post‐infection (p < 0.01 compared to 24 h)." (PMID 40940710, 2025). "Besides analyzing ferroptosis-related protein markers, this cohort study also evaluated traditional biochemical indicators of infection, including IL-1β, IL-6, IL-8, IL-10, CXCL2, and TNF-α." (PMID 40264754, 2025). "Anti-inflammatory cytokine IL-10 was most highly expressed at 7 DPC in primary infection mice." (PMID 41190814, 2025). "Moreover, adding excess amounts of iron during an infection with Salmonella influences a multitude of metabolic pathways, pointing in the direction that a reverse conclusion concerning IL-10 expression in Tim3−/− mice should be drawn cautiously." (PMID 40939292, 2025). "However, at 3 months, increased fold change of cytokines IL‐31 (P = 0.0135) and IL‐10 (P = 0.0365) were correlated with subsequent infection." (PMID 40766049, 2025). "HBoV1 infection increases the concentrations of IL-2, IL-4, IL-10, and IL-13 in patients." (PMID 39846742, 2025). "Additionally, MDSC-like cells recruited during KPPR1 infection appeared to aid in clearing apoptotic neutrophils via efferocytosis, producing IL-10 to enhance lung recovery." (PMID 40096073, 2025). "Longitudinal monitoring of these chimpanzees over the past 6 years revealed that infected individuals often experienced persistent or recurrent infections (unpublished data), supporting a role for IL-10 in the ongoing regulation of immune responses during chronic exposure." (PMID 41279035, 2025). "Delta‐infected males showed increased pulmonary infiltration of CD163+ “M2” macrophages, Ly6G+ neutrophils, and NKR‐P1C + NK cells during early onset of infection, and elevated lung inflammatory cytokines such as IL‐10, IL‐6, and IP‐10 than Delta‐infected females." (PMID 40686017, 2025). "Upon further investigation, we found that specific cytokines, chemokines and growth factors could be correlated with subsequent infection: IL‐10, IL‐31, ENA‐78, fractalkine, MCP‐2, HGF and MMP‐1." (PMID 40766049, 2025). "This could be related to better control of infection in viral reservoirs, such as tissue macrophages, which would result in less chronic activation of the immune system and consequently lower IL-10 production." (PMID 40367013, 2025). "In early infection, IL-10 may inhibit the production of pro-inflammatory cytokines, boost bacterial dissemination to the bloodstream, and could be exploited by pathogens to facilitate their survival." (PMID 39770719, 2024). "For example, recombinant surface antigen SAG1 (rSAG1) reduced fetal infection in resistant mice, but not in susceptible animals, although similar levels of cytokines such as IL-4, IL-10, and IFN-γ were observed in maternal sera during gestation." (PMID 39597754, 2024). "Analysis of IL1b and IL10 expression revealed that infection of wild-type mouse macrophages NR-9456 with S. epidermidis 1457-M10 and 1457ΔatlE induced a strong IL1b expression, which was slightly lower after infection of TLR9−/− mouse macrophages." (PMID 39567551, 2024). "The results demonstrated that, influenced by the liver parasitic infection, pro-inflammatory factors IL-1β and TNF-α exhibited continuous increases in both serum and liver levels at all infection stages, while anti-inflammatory factors IL-4 and IL-10 showed persistent decreases." (PMID 39749332, 2024). "Moreover, by the 7th day post-infection, the mortality rate of the mice reached 50.0%, indicating complex immune regulatory mechanisms, including overexpression of IL-10 and increased production of pro-inflammatory cytokines like TNF-α." (PMID 39129003, 2024). "Our data reiterate the importance of these innate-like cells, with γδ T cells contributing to the enhanced effector cytokine production seen in both the systemic and s.c. infection setting and IL-10 blockade also resulting in improved cytokine responses from these cells." (PMID 38973612, 2024).
infection (continued). "Notably, the hepatic expression of type I and type II cytokines like Tnfα, Ifnγ, Il12, or Il4, as well as regulatory cytokines like Il10, showed maximum expression at the youngest age of infection similar to egg load and granuloma extent." (PMID 39404406, 2024). "In this context, yeast products may alter secondary immune responses, as shown by the increase in IL-10 production after 2 and 4 h of infection with L. braziliensis in macrophages." (PMID 38396599, 2024). "Moreover, there was only a significant reduction in anti-inflammatory IL-10 production upon Sirt1 and Sirt3 knockdown at 2 hr and 20 hr post-infection." (PMID 39693143, 2024). "Moreover, TLR2 ‘Agonist’ Pam3CSK4 improved the ratio of IL10/ TNFα which known to be protective against infection." (PMID 39729468, 2024). "As opposed to the polymorphisms in PTX3, the rs3024491 in IL-10 and rs2853550 in IL-1β were strongly associated with the infection status." (PMID 38790226, 2024). "By promoting Treg development and IL-10 production, the immune system can effectively control Salmonella-induced inflammation while minimizing collateral tissue damage, thereby facilitating the resolution of the infection and promoting overall gut health." (PMID 39204243, 2024). "IL-10–mediated inhibition of shedding GC-associated cervical epithelial cells in the presence of the potent inflammatory cytokines IL-1β and TNF-α underscores the importance of the direct interaction of IL-10 with IL-10R on epithelial cells for GC-establishing infection at the human cervix." (PMID 39585777, 2024). "NK cell-derived IL-10 production can be detrimental by inhibiting protective immune responses against pathogens and might therefore promote infection persistence and aggravation." (PMID 39355242, 2024). "IL-10 is an extremely effective anti-inflammatory cytokine that plays a crucial role in the regulation from the autoimmunity and the inflammatory responses during infection with viruses, bacteria, fungi and parasites." (PMID 39598280, 2024). "This may aid in limiting host-induced tissue damage, as IL-10 inhibits chemokine production by immune cells, indirectly downregulating cell recruitment to infection sites." (PMID 39650648, 2024). "Similarly, matching CRP with IL-10 levels, the clinician obtained a higher discriminative ability in the etiology of infection (specificity from 77% to 98%, sensitivity 75%)." (PMID 38254697, 2024). "Deletion of TLR9, however, did not attenuate IL10 induction after infection with S. epidermidis 1457, while being associated with a significantly increased IL10 expression after infection with 1457-M10 and 1457ΔatlE." (PMID 39567551, 2024). "In addition, a newly identified population of human cord blood CD5hi cells was found to secrete IL-10 upon infection by the respiratory syncytial virus and subsequently, more adverse clinical outcomes." (PMID 39312581, 2024). "Il10 mRNA revealed statistically significant peaks at day 2 and 8 post-infection, while the mRNA expression of Tgfβ had one main significant peak in the acute phase of inflammation on day 2 post-infection." (PMID 39355243, 2024). "A factor analysis study in Zimbabwean children similarly found that a composite variable representing IL-5, IL-10, and IFN-γ increased with age and was positively associated with current Sh infection as well as with past Sh exposure determined by the presence of Sh-specific antibodies in serum." (PMID 39250522, 2024). "However, alveolar macrophages that express the IFNAR2-IL-10RB hybrid receptor upregulate ACE2 expression under IL-10 stimulation, becoming more susceptible to SARS-CoV-2 replicative infection." (PMID 39770368, 2024). "The mRNA level of IL-10 was downregulated in the pre-infection and post-infection assays." (PMID 38791551, 2024). "Our results lead to a hypothesis that GC induce early and local IL-10 production in the cervix to promote asymptomatic infection in women." (PMID 39585777, 2024).
infection (continued). "Tetramerization of the PKM2 monomer/dimer counteracts the LPS-induced increase in glycolysis and modulates the host immune response in vivo by attenuating IL-1β production and promoting IL-10 secretion, leading to an increase in bacterial transmission and impaired infection clearance." (PMID 38755659, 2024). "However, long-term infection drives the immune system towards a Th2 response with high levels of IL-4, IL-5, IL-13, and immunosuppressive IL-10 and TGF-β, leading to tolerance." (PMID 38817444, 2024). "Increased IL-10 production has been demonstrated in response to infections by Plasmodium spp." (PMID 39770782, 2024). "We tested the hypothesis that during infection Il10 expression governed crosstalk between Bregs and microglia in the brain, using smFISH and FISHtoFigure to investigate the localisation of transcripts." (PMID 38594373, 2024). "In addition to the role of IL-10 during infections, IL-10 play a critical role in establishing SA nasal colonization." (PMID 38786139, 2024). "Moreover, anti-IL-10R treated WT mice mirrored the phenotype of Il10-/- mice, indicating that antibody-mediated IL-10R blockade has similar biological effects as IL-10 cytokine knockout in this infection model." (PMID 38271477, 2024). "In addition to glucocorticoids, there are other factors such as galectin-1, prolactin, progesterone, and IL-10 have been reported to inhibit infection-induced inflammatory responses in the intrauterine tissues." (PMID 39290694, 2024). "During infection, IL-10 inhibits the activity of Th1 cells, NK cells, and macrophages." (PMID 38250904, 2024). "Moreover, hylB enables GBS to induce immune suppression in a TLR2/4- and interleukin-10 (IL-10) -dependent manner, leading to increased rates of ascending infection and preterm birth." (PMID 39722064, 2024). "When infection or injury is controlled, macrophages initiate M2 polarization and secrete anti-inflammatory molecules, including IL-1 receptor antagonists (IL-1RA) and IL-10." (PMID 38434258, 2024). "In the other hand, during the infection course, tissue inflammation characterized by a pro-inflammatory Th17 profile with an expression of RORγt, IL-17, IL-10 and IL-6 significantly increased in the middle stage (day 30-90) in a mouse model of Echinococcus infection." (PMID 38817444, 2024). "This phenomenon, called ‘infection tolerance,’ is initiated by neutrophil-LPS-stimulated Treg interaction, which results in the repolarisation of neutrophils to IL-10-positive cells, which, in the second phase, induces other IL-10-secreting neutrophils in a paracrine manner." (PMID 38745328, 2024). "We propose a method of improving vaccine efficacy by inhibiting IL-10 production during the vaccination, which leads to enhanced antigen-specific T cell responses and improved bacterial clearance in both the systemic and s.c. infection settings." (PMID 38973612, 2024). "The anti-inflammatory cytokine IL-10 is produced by T lymphocytes, which inhibit the production of pro-inflammatory cytokines and prevent neutrophils and macrophages from infiltrating an infection." (PMID 38792366, 2024). "Indeed, even NK cells and CD4+ T cells will become important IL-10 producers in the later stages of the infection as a consequence of persistent and extensive activation." (PMID 39359727, 2024). "The expression levels of interleukin 1 beta (IL-1β), IL-6, IL-8, IL-10, IL-17A, and the interleukin receptor IL-17RA were significantly increased after infection with Yb2 and cYb2ΔsspA and were much greater than those in the brains of control and Yb2ΔsspA-infected ducks at 24 and 48 hpi." (PMID 38594770, 2024). "Increased production of TNF-α and IL-12 during infection in the presence of IL-10 neutralizing antibodies further supports the hypothesis and paves avenue to explore the interdependency of IL-33 and IL-10." (PMID 38750790, 2024).
infection (continued). "The GPNMB functions to reduce inflammation by increasing anti-inflammatory cytokines like IL10 and decreasing proinflammatory cytokines like TNFα, IL-6, and IL-12, which aid in response to lesions in the tissue or infection, and can be triggered by pathogens that are present in their environment." (PMID 39744066, 2024). "In parallel, compared to infection with 1457ΔatlE without exogenous DNA-supplementation, IL1B was significantly reduced, while there was a significant induction of IL10 expression (mean fold change: 1.156 ± 0.85) expression levels reminiscent of findings in untreated S. epidermidis 1457 infection." (PMID 39567551, 2024). "To determine the mRNA expression levels of IFN-γ, TNF-α, IL-1β, and IL-18, as well as the abundance of cytokines IFN-γ, TNF-α, IL-6, and IL-10 in the kidneys of uninfected and PbA-infected mice at day 7 post-infection, we performed quantitative real-time PCR and CBA assays, respectively." (PMID 38787228, 2024). "Research into the bacterial factors that drive IL-10 production could offer insights crucial for designing effective preventive measures against SA infections." (PMID 38786139, 2024). "Mice were immunized with LP1569 (50 μg) + cGMP (10 μg) only; vaccine only, consisting of LP1569 (LP) + cGMP + ClfA (5 μg); vaccine + anti–IL-10 (150 μg); or vaccine + isotype control (150 μg), following the same regimen of injections and subsequent s.c. infection on day 42 with LAC (2 × 107 CFU)." (PMID 38973612, 2024). "Sa induces IL-10 in conjunction with colonization, biofilm formation, and infections." (PMID 39680460, 2024). "However, compared to Tg infected animals, HpTg infected animals only had decreased levels of MLN Ifnγ and SI2 Il-10 at day 5 post Tg infection, despite increased Il-4 and Il-13 in the SI, PP, MLN and SPL." (PMID 38950025, 2024). "IL-8 and IL-10 can be used to predict the infection severity." (PMID 38173531, 2024). "In the three dietary supplemented groups with UROEE, CsNPs and UROEE-CsNPs, the mRNA expression level of IL-10 was significantly (P < 0.05) decreased following primary infection by (~ 0.42, 0.52 and 0.67-fold, respectively) at 6 DPPI, when compared to NC group." (PMID 38492183, 2024). "The study indicated that zebrafish infected with A. hydrophila showed increased IL-10 and IL-4 expressions in the early stages of infection to alleviate inflammation, decreased in subsequent stages after successfully mitigating the bacteria, and later increased again to maintain body homeostasis." (PMID 39185043, 2024). "Additionally, the release of EVs in the sandfly midgut and their co‐inoculation during host infection exacerbate cutaneous lesion pathology by increasing the production of cytokines, including IL‐2, IL‐4, IL‐10, IL‐17, IL‐23 and IFN‐γ." (PMID 39113589, 2024). "In another study, it is proposed that the cytokine IL-10 can stimulate the production of IgG 4 during infections; however, the role of IgG 4 in infectious diseases is unclear, as it may be associated with pathogenicity or protection in different disorders." (PMID 39495782, 2024). "Moreover, the Th2-specific cytokine Il4 and the immunomodulatory cytokine Il10 were induced with infection and most pronounced when the infection occurred at an early age." (PMID 39404406, 2024). "However, during the muscle stage of infection, there was a shift towards a Th2 response, characterized by the production of cytokines such as IL-4, IL-10, and IL-13, which were involved in regulating inflammation and tissue repair." (PMID 38166140, 2024). "AgNPs could improve the immune response of mice against infection by elevating the serum levels of IL-10 and INF-γ60." (PMID 38724594, 2024). "In some cases, the high expression of IL-10 may inhibit the effective clearance of pathogens by the immune system, leading to the persistence or aggravation of infection." (PMID 38872795, 2024).
infection (continued). "We could deduce that perhaps, at 6 and 12 h post-infection, macrophages attempt to inhibit IL-10 production in favor of promoting IL-12 production." (PMID 38299832, 2024). "IL-10 is produced by a variety of cell types, and its primary cellular source might change depending on the tissue or infection stage." (PMID 38535313, 2024). "However, this was analyzed at 3 weeks of infection, a time where IL-10 is highly produced by conventional CD4 T memory cells and M09 cells are far from peak levels, and IL-10 suppresses MHC-Il during MCMV infection." (PMID 38236791, 2024). "However, IL-10 and TGF-β1 were highly expressed in both phases of infection, and their expression was linked to antibody production but not moderation of pro-inflammatory cytokine responses." (PMID 38803499, 2024). "In addition, previous studies have shown that the IL10 gene is the main regulator of infection immunity." (PMID 39596441, 2024). "Although this result could be interpreted in many ways, it could be consistent with increased IL-10 in the context of SA infection that facilitates greater SA survival." (PMID 39681568, 2024). "Additionally, IL-10 plays a crucial role in facilitating tissue healing after infection or inflammation." (PMID 39336593, 2024). "The analysis of cytokine levels in relation to the febrile stage and the type of infection revealed that IL-6 and IL-10 concentrations were elevated in Ph I from secondary infections compared to Ph I in primary infections (p = 0.005 and p < 0.001, respectively)." (PMID 39457019, 2024). "Through various signaling and metabolic pathways, ESAT6 participates in the inhibition of autophagy, in the triggering of necrosis, and in the stimulation of the production of cytokines IL-6, IL-1β, and IL-10 for the creation of a chronic proinflammatory background at a site of infection." (PMID 39591170, 2024). "Finally, when the human cytokine profile was analyzed in the Hu-SGM3-PBMCs model, there was a detection of high concentrations of IFN-γ (2/3 mice) and the anti-inflammatory cytokine IL-10 (3/3 mice) by day 7 post-infection." (PMID 39204240, 2024). "We may suggest that infection with E. canis and A. phagocytophilum stimulates the IL-10 production in dogs, which may facilitate specific antibody responses." (PMID 39770719, 2024). "IL-10 functions in the setting of infections by suppressing the function of macrophages, natural killer (NK) cells, and Th1 cells—all of which are necessary for efficient pathogen clearance but may potentially exacerbate tissue damage." (PMID 38535313, 2024). "Notably, 16 interleukins, excluding IL-10, exhibited elevation in the brain during infection, contrary to expectations based on previous studies." (PMID 38399983, 2024). "Continuously high concentrations of serum TNFα and IL-6 at the early infection course, as well as low IL-10, were detected in lnc-ip65−/− mice, suggesting that excessive inflammatory responses occurred and might contribute to the lethal pathogenesis." (PMID 38200007, 2024). "Moreover, the immunosuppressive effect of IL-10 in regulating immune responses during infection with intracellular pathogens is well documented." (PMID 39199857, 2024). "Moreover, our transcriptional analysis detected relatively few changes in the response of BAL cells during the early phase of infection after IL-10 blockade." (PMID 38950078, 2024). "Considering the expression of IL-10 by MDSCs recruited to the lungs of infected mice, the only difference observed between WT and TLR4KO animals was a lower frequency of IL-10+ M-MDSCs in TLR4-deficient mice after 72 hours of infection." (PMID 39035356, 2024). "This IL-10 producing activity in B cells is inversely correlated with specific IgE production towards ABA-1, a trait that has been previously linked with resistance to infection." (PMID 39312581, 2024). "Notably, M-CSF showed a remarkable increase only in PLF, while IL-10 exhibited a notable increase only in serum after infection." (PMID 38951957, 2024).